SMARCA4 (SWI/SNF related BAF chromatin remodeling complex subunit ATPase 4)
Diseases named in the same sentence as SMARCA4 in open-access papers (continued):
Sharing a sentence is not in itself a finding about the gene and the disease.
small cell carcinoma of the ovary (continued). "In particular, up to 90% of a rare form of OC, small cell ovarian carcinoma, hypercalcemic type (SCCOHT), a rhabdoid-like tumor has germline or somatic mutations of SWI/SNF ATPase domain BRG1 coding gene SMARCA4." (PMID 36430148, 2022). "Small cell carcinoma of the ovary, hypercalcemic type (SCCOHT) is a rare and aggressive condition that is associated with the SMARCA4 mutation and has a dismal prognosis." (PMID 35200537, 2022). "We show that they form a separate group segregating from SMARCB1 mutated ATRTs and from other SMARCA4-deficient tumors like small cell carcinoma of the ovary, hypercalcemic type (SCCOHT) or SMARCA4 mutated extra-cranial malignant rhabdoid tumors." (PMID 33331994, 2021). "In small cell carcinoma of the ovary, hypercalcemic type (SCCOHT), loss of the SMARCA4 protein has been proposed to be the main driving event in tumorigenesis." (PMID 33331994, 2021). "Because SMARCA4 deficiency is common in small cell ovarian cancer, Burkitt lymphoma and pediatric medulloblastoma, among other tumor types, ATRi monotherapy may be effective and specific against other SMARCA4-deficient cancer cells with minimal undesirable effects." (PMID 34316685, 2020). "Inactivating mutations in SMARCA4 (BRG1), a key SWI/SNF chromatin remodelling gene, underlie small cell carcinoma of the ovary, hypercalcemic type (SCCOHT)." (PMID 30718512, 2019). "We and others uncovered that small cell carcinoma of the ovary, hypercalcemic type (SCCOHT), a rare and often lethal cancer of young women, is almost always caused by biallelic deleterious mutations in SMARCA4, leading to loss of SMARCA4 protein expression." (PMID 30718512, 2019). "In our previously published work on small cell carcinoma of the ovary, hypercalcemic type (SCCOHT), we showed that only one gene – SMARCA4 – was recurrently mutated in our case cohort and was responsible for this disease." (PMID 28416765, 2017). "Concerning the role of SMARCA4 in cancer, BRG1 deficiency is implicated in the development of several malignancies, such as small-cell carcinoma of the ovary hypercalcemic type (SCCOHT), SMARCA4-deficient thoracic sarcoma, colorectal cancer, and endometrial stromal sarcomas." (PMID 38542211, 2024). "SMARCA4 (BRG1) deficiency has been reported in several malignances, including small cell carcinoma of the ovary, hypercalcemic type (SCCOHT), lung adenocarcinoma, medulloblastoma, Burkitt lymphoma, breast cancer, uterine sarcoma, and thoracic SMARCA4-deficient undifferentiated tumors (SMARCA4-UT)." (PMID 38877473, 2024). "Small cell carcinoma of ovary (SCCO) is a rare and aggressive cancer, primarily affecting adolescents and young women, usually accompanied with the hypercalcemic type (SCCOHT) and SMARCA4 mutation." (PMID 36742399, 2023). "Genetic profiling has demonstrated these mutations in small cell carcinoma of the ovary and hypercalcemic type (SCCOHT) and SMARCA4-deficient undifferentiated uterine sarcoma, as well as atypical teratoid rhabdoid tumors, malignant rhabdoid tumors, and aggressive SMARCA4-deficient thoracic sarcomas." (PMID 35320498, 2022). "Interestingly, SMARCB1-mutant rhabdoid tumors and SMARCA4-mutant small cell carcinoma of the ovary have an immune active microenvironment and are responsive to immune-checkpoint inhibition." (PMID 34359794, 2021). "Small cell carcinoma of the ovary, hypercalcemic type (SCCOHT) is driven by SMARCA4 loss." (PMID 30718512, 2019). "However, 2% of the MRTs and specific tumors, such as small cell carcinoma of the ovary, hypercalcemic type (SCCOHT), and SMARCA4-deficient thoracic sarcomas (SMARCA4-DTS), present dual deficiencies of BRG1 and BRM via a genetic loss of BRG1 combined with the silencing of BRM." (PMID 34070411, 2021). "SMARCA4/BRG1 deficiency has been detected in a wide variety of tumors, such as small cell carcinoma of the ovary, hypercalcemic type (SCCOHT) and thoracic SMARCA4 undifferentiated tumors." (PMID 38090508, 2023).
small cell carcinoma of the ovary (continued). "Small cell carcinoma of the ovary, hypercalcemic type (SCCOHT), is a rare SMARCA4-driven aggressive malignancy of young age characteristically associated with paraneoplastic hypercalcemia." (PMID 29158936, 2017). "Interestingly, in one of the miscellaneous tumor types—small-cell carcinoma of the ovary, hypercalcemic type (SCCOHT)—a striking dependence on SMARCA4 alterations has been observed, with up to 92% of cases." (PMID 41470247, 2025). "Absence of SMARCA4, which is typical of the small cell carcinomas of the ovary and occurs in some undifferentiated/dedifferentiated endometrial carcinomas, seems to be very infrequent in CRC." (PMID 33435234, 2021). "Notably, her sister had been previously diagnosed with small cell carcinoma of the ovary, hypercalcemic type (SCCOHT), a condition closely associated with germline SMARCA4 mutations, although no genetic testing had been performed at the time of her diagnosis." (PMID 39439958, 2024). "SMARCA2, SMARCA4, SMARCB1, ARID1A, ARID1B, and PBRM1 are subunits of the Switch/Sucrose non-fermenting (SWI/SNF) complex, which show frequent alterations in rhabdoid tumors, ovarian clear cell carcinomas (OCCCs), and small-cell carcinoma of the ovary, hyper-calcemic type (SCCOHT)." (PMID 34359794, 2021).
breast cancer (76 papers, 2008 to 2025). A primary or metastatic malignant neoplasm involving the breast. "In breast cancer, the knockout of the ATPase subunit SMARCA4 of the SWI/SNF chromatin remodeling complex is associated with cisplatin resistance in triple-negative breast cancer cells." (PMID 39609317, 2024). "Also, SMARCA4-null heterozygous mice spontaneously develop mammary tumors, and specific alleles of SMARCA4 are associated with cancer predisposition in humans." (PMID 34771636, 2021). "In addition, a high expression level of SMARCA4 or AURKA was associated with poor survival or metastasis-free survival in breast cancer patients." (PMID 34272397, 2021). "In line with our finding, SMARCA4 has also been found to be highly upregulated and promote cancer development in other organ systems, such as prostate cancer, breast cancer, liver cancer, gastric cancer and melanoma." (PMID 36902184, 2023). "A more recent study showed that an antisense lncRNA TGFB2-AS1 suppresses TGFB2 transcription in breast cancer cells through sequestering SMARCA4 (a SWI/SNF complex catalytic subunit) away from the TGFB2 promoter." (PMID 37858148, 2023). "Mechanistically, SMARCA4 has been reported to play an oncogenic role in breast cancer by regulating critical aspects of breast-cancer biology including lipid metabolism, proliferation, and resistance to chemotherapeutic drugs." (PMID 33837205, 2021). "The results of the CPTAC dataset showed higher expression of SMARCA4 total protein in the primary tissues of breast cancer, ovarian cancer, colon cancer, UCEC and LUAD (p< 0.001) than in normal tissues." (PMID 34675941, 2021). "The SMARCA4/BRG1 phosphorylation levels between tumor versus normal tissues of five types of tumors (breast cancer, clear cell RCC, LUAD, ovarian cancer, and UCEC) were analyzed using CPTAC dataset." (PMID 34675941, 2021). "Immunofluorescence staining results revealed that SMARCA4 expression was decreased to a greater extent in invasive breast cancer tissues compared with that in non-invasive breast cancer tissues." (PMID 34771636, 2021). "For example, down-regulation of SMARCA4 expression inhibited the proliferation, invasiveness, and motility of breast cancer cells in vitro and suppressed metastasis in breast cancer mouse models, suggesting a role of these genes in metastasis." (PMID 34272397, 2021). "However, SMARCA4 is also known to act as oncogene to promote tumorigenesis due to its high expression level found in certain cancers, including prostate cancer, breast cancer, liver cancer, and gastric cancer." (PMID 36902184, 2023). "Although SMARCA4 has been shown to regulate several oncogenic properties in breast cancer, the mechanisms by which it promotes these processes in mammary tumorigenesis, including potential effects on PI3K/Akt signaling, remains unknown." (PMID 33837205, 2021). "Profiling of the drug-able kinome in addition with transcriptome analyses suggest that SOX4 alone and in combination with SMARCA4 may modulate unique gene expression programs that contribute to breast-cancer genesis, progression, and response to therapy." (PMID 33837205, 2021). "Additionally, to confirm the clinical and biological significance of SMARCA4 in breast cancer patients, we compared the expression profiles of SMARCA4 in non-invasive breast cancer tissue versus invasive breast cancer tissue." (PMID 34771636, 2021). "SMARCA4, encoding a SWI/SNF catalytic ATPase subunit, is inactivated by mutations or other mechanisms in different cancers, including non-small cell lung cancer (NSCLC), breast cancer, glioblastoma, and others." (PMID 30718512, 2019). "Additionally, we identified the alterations of epigenetic targets, such as SWI/SNF related genes (SMARCA2, SMARCA4, SMARCA5) or histone modifiers (KMT2C or KMT2D), breast cancer-associated oncogenes (MYCN or MAPKs), or genes that are involved in drug-resistance (ESR1 and PIK3CA/B)." (PMID 31216647, 2019).
breast cancer (continued). "In breast cancer, miR-101 induced mild DNA damage and senescence by targeting UBE2N and SMARCA4, while severe damage reduced miR-101 expression and increased apoptosis." (PMID 40074445, 2025). "In breast cancer tissues, SMARCA2 (or BRM) and SMARCA4 (Brahma-related Gene 1, BRG1) ATPases were overexpressed, in most cases independently of the hormone receptor status." (PMID 35761157, 2022). "Based on this observation, it was postulated that expression of SMARCA2 and SMARCA4 has prognostic value, although another study shows that the BRM protein level varies among various breast cancer types." (PMID 31722744, 2019). "In contrast to SMARCA4-proficient ovarian controls, SCCOHT and ER+ breast cancer cell lines retain RB and express lower levels of the CDK4/6 inhibitor p16INK4a, a profile that has been associated with positive responses to palbociclib." (PMID 30718512, 2019). "Given that our data identifies SOX4 and SMARCA4 as key modulators of TGFBR2 expression and PI3K activity in basal-like breast cancer, it remains to be determined if aberrant TGFBR2 activity can also regulate a similar resistance mechanism to PI3K-family inhibitors in TNBC patients." (PMID 33837205, 2021). "Several BrD members, namely BRPF1, SMARCA4, BRD7, BRD9, BAZ1B, ATAD2 and BRD4 are significantly upregulated in basal breast cancer subtype (when compared to less aggressive luminal A and normal‐like subtype), which strongly mimics the results obtained for the mRNA‐SI." (PMID 35049055, 2022). "Therefore, the observation that SOX4 and SMARCA4 mediate PI3K activity through TGFBR2 expression identifies a novel and direct role for TGFBR2 in activating noncanonical PI3K signaling in basal-like breast cancer." (PMID 33837205, 2021).
malignant rhabdoid tumors (70 papers, 2014 to 2026). "Typically, rhabdoid tumors can be classified as SMARCB1 deficient by demonstrating loss of INI-1 or as SMARCA4 deficient by demonstrating loss of BRG-1." (PMID 40036664, 2025). "Specifically, ASPS showed a partial response rate of 50%, while SMARCA4-deficient sarcomas and malignant rhabdoid tumors exhibited a 25% partial response rate." (PMID 40075735, 2025). "Our data demonstrate a loss of SWI/SNF occupancy at SEs with SMARCA4 re-expression, which is in contrast to what is observed in rhabdoid tumors." (PMID 39906560, 2025). "Germline heterozygous loss-of-function mutations in the SMARCA4 gene can result in rhabdoid tumor predisposition syndrome-2, which is associated with an increased risk of developing atypical teratoid/rhabdoid tumors and SCCOHT." (PMID 39064514, 2024). "Given that atypical teratoid/rhabdoid tumors induced by the SMARCA4 gene mutation are a rare and aggressive type of cancer, they are associated with an unfavorable prognosis, and the exact prevalence is difficult to define." (PMID 40729139, 2024). "Germline mutations in SMARCA4 have been implicated in a range of malignancies, including rhabdoid tumor predisposition syndrome 2 (RTPS2) and SCCOHT." (PMID 39439958, 2024). "Other SMARCA4-deficient malignant tumors, such as malignant rhabdoid tumor (MRT) and SCCOHT, differ from SMARCA4-UT in tumor extension and patient age, occurring mostly in young children." (PMID 38542211, 2024). "A total of 98 patients were enrolled in the sarcoma cohort, including 34 with chordoma, 14 with ASPS, 11 with SMARCA4-deficient malignant rhabdoid tumor (SMRT), 8 with desmoplastic small round cell tumor (DSRCT) and 31 with other histotypes." (PMID 37190214, 2023). "Another study, the AcSé trial, showed 50% ORR in the subgroup of SMARCA4-deficient rhabdoid tumors, higher than in other rare sarcomas included." (PMID 37446319, 2023). "With the presence of larger cells resembling malignant rhabdoid tumor, recurrent SMARCA4 mutations, SCCOHT is the unique subtype that does not belong to the family of neuroendocrine tumors but resembles malignant rhabdoid tumor." (PMID 36290894, 2022). "Carriers of heterozygous constitutional mutations of SMARCB1 or SMARCA4 are prone to develop rhabdoid tumors (RT), which have been clinically named as rhabdoid tumor predisposition syndromes 1 (RTS1) and 2 (RTS2), respectively." (PMID 35320498, 2022). "In a meta-analysis of publicly available data sets, Holsten and colleagues detected SMARCA4 PVs as the cause of a rhabdoid tumor in 8/60 PV carriers, indicating incomplete penetrance." (PMID 33532948, 2021). "SMARCA4 mutations were also identified in patients with rhabdoid tumor predisposition syndrome, characterized by a high risk of developing rhabdoid tumors." (PMID 34042280, 2021). "Among the five posterior mediastinal tumors, there were three neuroblastomas, one malignant rhabdoid tumor, and one SMARCA4-deficient thoracic sarcoma." (PMID 32522190, 2020). "There were four stage 3 non-Hodgkin lymphoma, three stage 3 neuroblastomas, two acute lymphocytic leukemias, and three other tumors (malignant rhabdoid tumor, Langerhans histiocytosis, and stage 4 SMARCA4-deficient thoracic sarcoma)." (PMID 32522190, 2020). "Families with germline SMARCA4 mutations have been reported to develop malignant rhabdoid tumors (SCCHT, AT/RT, renal rhabdoid tumor) and yolk sac tumor (YST), all belonging to the group of embryonal tumors." (PMID 25886974, 2015). "A pivotal advancement followed with the discovery of another SWI/SNF chromatin-remodeling complex member associated with Rhabdoid Tumors in infancy—the ATPase subunit SMARCA4 (BRG-1)—leading to the recognition of a second histologic subtype: SMARCA4-mutant AT/RT." (PMID 41374972, 2025).
malignant rhabdoid tumors (continued). "While a few studies have reported on undifferentiated carcinoma or rhabdoid tumors with SMARCA4 mutations in the gastrointestinal tract, the specific association between SMARCA4 mutations and clinicopathological factors or patient survival in GEA has not been fully elucidated." (PMID 38610978, 2024). "Unlike primary rhabdoid tumors, such as malignant rhabdoid tumors, atypical teratoid/rhabdoid tumors, SMARCA4-deficient thoracic sarcomas, and epithelioid sarcoma, which often show alterations in SMARCB1 (INI1) or SMARCA4, cutaneous RSCC does not exhibit such inactivation." (PMID 39677213, 2024). "Kaposi and other rare forms of sarcoma, such as chordoma and SMARCA4-deficient rhabdoid tumors, might also benefit from PD1 inhibitors." (PMID 37190214, 2023). "Another example of mutation in SMARCA4 that has been associated with an increased risk for developing a malignant type of soft tissue tumor called rhabdoid tumor is that germline heterozygous loss-of-function mutations in SMARCA4 (19q13.2) cause rhabdoid tumor predisposition syndrome II." (PMID 34771683, 2021). "Acase report on the long-lasting response of Pembrolizumab showed that a 58-year-old woman diagnosed with a SMARCA4-deficient malignant rhabdoid tumor-like tumor, characterized by dual loss of SMARCA4 and SMARCA2 on IHC had remarkable symptomatic recovery from the treatment." (PMID 34440689, 2021). "As we have demonstrated, rhabdoid tumors may develop in association with the immature teratoma and this neoplasm may be observed in the SMARCA4 mutation carriers." (PMID 25886974, 2015). "Additionally, in families with a known pathogenic SMARCA4 variant, genetic counseling can guide risk assessment for other related malignancies (for example, rhabdoid tumors) that may also be associated with SMARCA4 loss." (PMID 40896427, 2025). "Histologically, SMARCA4‐UT tumors are characterized by undifferentiated features, marked nuclear atypia, prominent nucleoli, pleomorphism, and rhabdoid cells, resembling malignant rhabdoid tumors." (PMID 41577374, 2026). "In terms of their clinicopathological and genetic characteristics, these tumors overlap with other SMARCA4-deficient cancers, such as ovarian small cell carcinoma of hypercalcemic type (SCCOHT), atypical teratoid/rhabdoid tumors, and thoracic sarcomas." (PMID 39064514, 2024). "An R1 resection was performed and an ovarian malignant rhabdoid tumor arising in the context of a germline SMARCA4 alteration was confirmed." (PMID 38062114, 2023). "Rhabdoid tumors with specific SWI/SNFc subunit mutations (mostly SMARCB1 and SMARCA4) have been shown to be associated with immune infiltration in the tumor microenvironment, monocytes/macrophages and CD8+ T lymphocytes being the two most predominant subtypes." (PMID 37446319, 2023). "Conversely, while nearly all cases of extracranial rhabdoid tumors harbored mutations of SMARCB1, SMARCA4 mutations were only observed in approximately 0.5%–2% atypical teratoid/rhabdoid tumors." (PMID 38124509, 2023). "For example, SMARCA4-deficient ovarian small-cell carcinomas and SMARCB1-deficient malignant rhabdoid tumors display sensitivity to EZH2 inhibitors." (PMID 36361605, 2022). "Rhabdoid tumors share germline and somatic mutations in SMARCB1 or, more rarely, SMARCA4, members of the SWI/SNF chromatin-remodeling complex." (PMID 33692948, 2021). "SMARCB1 and SMARCA4 are tumor suppressor genes playing a critical etiologic role in all rhabdoid tumors including AT/RT, which is linked to somatic and germline mutations of SMARCB1 or, more rarely, SMARCA4." (PMID 33692948, 2021). "Concomitant loss of SMARCA4 and SMARCA2 expression is also a feature of SMARCA4-deficient thoracic sarcomas (SMARCA4-DTS) and of a subset of malignant rhabdoid tumors (MRTs)." (PMID 32575483, 2020).